LINC01525 (long independently transcribed non-coding RNA 1525)
Synonyms: lnc-MAN1A2-1
Gene: Long non-coding RNA gene on chromosome 1 (117,272,182 to 117,321,339, forward strand). Ensembl gene ENSG00000235202.
Diseases named in the same sentence as LINC01525 in open-access papers:
LINC01525 is named in the same sentence as 3 diseases in open-access papers, as found by Europe PMC text mining. Sharing a sentence is not in itself a finding about the gene and the disease.
LINC01525 shares sentences with these, for which no sentence is quoted: cancer (1 paper); renal carcinoma (1); tumour (1).